TNF (tumor necrosis factor)
Diseases named in the same sentence as TNF in open-access papers (continued):
Sharing a sentence is not in itself a finding about the gene and the disease.
neurological diseases (continued). "Increase of TNF-α, a central mediator of neuroinflammation, occurs with the onset of early neurological diseases, which develop typical pathologies in age-related neurological diseases." (PMID 31991572, 2020). "This review summarizes the evidence on the pathophysiological role of TNF in MS and in different MS animal models, with a special focus on pharmacological treatment aimed at controlling the dysregulated TNF signaling in this neurological disorder." (PMID 33066433, 2020). "Increased levels of TNF-α in the blood activates matrix metalloproteinase 9 (MMP-9), which causes blood-brain barrier (BBB) disruptions and induces related neurological disorders." (PMID 31991572, 2020). "Proinflammatory cytokines, including TNF-α and IL-6, are produced after microglial activation and their abnormal production or functions in the brain are characteristic of various neurological diseases." (PMID 31336605, 2019). "Neurological side effects have been reported and recent data suggest a role for anti-TNF drugs in the induction of neurological disease, especially demyelination of the CNS as well as implications at the level of the peripheral nervous system." (PMID 29751683, 2018). "As in several other neurological disease, increased levels of TNF and sTNF(R1) are evident in the CSF and tissues of PD patients, as well as in postmortem brain tissue." (PMID 29751683, 2018). "Their connectivity map included interleukin-6 (IL-6) and tumour necrosis factor α (TNF-α) as central nodes and the pathway identified with the highest score was involved in neurological disease, psychological disorders, and cellular movement." (PMID 29301248, 2018). "Inflammatory mediators such as interleukin-1β (IL-1β), interferon-γ (IFN-γ), tumor necrosis factor-α (TNF-α), and NO are produced by activated microglia and have recently been linked to the pathogenesis of neurological disorders." (PMID 30510627, 2018). "Nonetheless, also non-neurological diseases will benefit from receptor-discriminatory drugs as pan-TNF neutralization induces neurological phenomena in some patients." (PMID 29751683, 2018). "High levels of pro-inflammatory cytokines such as TNF-α, IL-6, and IL-1β were found elevated in the brain tissue from patients with neurological diseases." (PMID 29719536, 2018). "Growing evidence showed that the overproduction of TNF-α by microglia contributes to pathophysiological changes observed in various neurologic diseases and brain injury." (PMID 28542400, 2017). "The potential involvement of NF-κB and STAT3 was investigated because the promoters of both TNFα and IL-6 contain binding sites for NF-κB and STAT3, which are known to be involved in neurological disorders associated with increased inflammation." (PMID 29228978, 2017). "In line with this, elevated brain protein levels of TNF-α, IL-1β, and IL-6 have been reported in rodent mTBI models as well as within human CSF within hours of injury, as they have in other neurological disorders." (PMID 25879458, 2015). "Taken together, these studies support an important role for TNF-α in neuroinflammation and the modulation of neuronal function and viability across a broad range of neurological disorders." (PMID 25879458, 2015). "In other neurological diseases, upregulation of neuronal TNF expression has provided an indication to the severity of disease progression and inflammatory neuropathology." (PMID 26112704, 2015). "In pathological conditions, microglia release large amounts of TNF-α; this de novo production of TNF-α is an important component of the so-called neuroinflammatory response that is associated with several neurological disorders." (PMID 24966471, 2014). "It is interesting to note that, in those neurological disorders in which neuroinflammation and increased levels of TNF-α have been described (see Section 1), it has also been reported a reduced expression of GLT-1, GLAST, or both." (PMID 24966471, 2014).
neurological diseases (continued). "Brain and cervical spine magnetic resonance imaging (MRI) and neurophysiological tests were performed in all patients before the initiation of anti-TNFα therapy and after a mean of 18 months or when clinical symptoms and signs indicated a neurological disease." (PMID 24938855, 2014). "Over-activated microglial cells cause overproduction of various proinflammatory cytokines including tumor necrosis factor-alpha (TNF-α), interleukin 1β (IL-1β) and chemokines, which are believed to contribute to HIV-1-associated neurologic disorders." (PMID 23936448, 2013). "TNF produced by activated glial cells in inflammatory or degenerative neurological diseases affects neurites by acting on the kinesin-tubulin complex and inhibiting axonal mitochondria and synaptophysin transport via JNK in hippocampal cultures." (PMID 23776493, 2013). "Novel research has also demonstrated the involvement of IL-1β, IL-2, IL-8, and TNFα dysfunction in neurological diseases including attention-deficit hyperactivity disorder (ADHD) and delayed cognitive development." (PMID 22768323, 2012). "Elevated levels of TNF-α and activation of TNF-α-mediated signaling pathways are evident in a large number of neurological disorders including AD, PD, and ALS." (PMID 20950451, 2010). "HIV infected macrophages or restrictively infected astrocytes release TNFα into the extracellular milieu and is a key inflammatory mediator in models for the observed chronic inflammation in HIV Associated Neurologic Disease (HAND)." (PMID 19009018, 2008). "TNF-targeted therapies, however, have largely failed in the treatment of neurological diseases, possibly due to the often-antithetic functions of the two TNF receptors and, importantly, to the limited knowledge regarding the exact contribution of microglial TNFR2 signaling after CNS injury." (PMID 38142915, 2024). "TNF‐α has been reported to be both neurotoxic and neuroprotective in nervous system diseases." (PMID 37789643, 2024). "Additional articles continue to be published correlating anti-TNF agents with neurological disease." (PMID 39078559, 2024). "Additionally, their correlation analysis indicated positive correlations between serum miR-128 levels and serum IL-1β and the TNF-α levels in neurological disorder patients." (PMID 38541185, 2024). "However, anti-TNF-α therapeutic endeavors failed for neurological disorders but were quite successful in the treatment of various autoimmune diseases." (PMID 37355890, 2023). "Moreover, TNF can act through TNF receptor-2 (TNF-R2), which is minimally expressed physiologically in the CNS but is upregulated in neurological diseases." (PMID 37242611, 2023). "It is also recognized that in addition to PD, TNF-α also contributes a sustained astrogliosis in multiple neurological diseases, such as stress and traumatic brain injury, suggesting that TNF-α-mediated astrogliosis is an integral player in the pathogenesis of a variety of neurological diseases." (PMID 37674228, 2023). "Neuroinflammation is a key component of various neurological diseases and the levels of most central and peripheral pro-inflammatory markers, such as C-reactive protein and tumor necrosis factor α (TNFα), are increased in depressed patients and decrease to normal levels after recovery." (PMID 35449567, 2022). "Many neurological disorders appear to share a neuroinflammatory component, and chronic TNF-α expression has been observed in neurodegenerative disorders such as multiple sclerosis, amyotrophic lateral sclerosis, PD, AD, ischemia, as well as in various forms of dementia." (PMID 33854417, 2021). "Differences between the central and peripheral functions of TNFα, as well as signaling via TNF receptor 1 (TNFR1) versus TNFR2, may be responsible for the contrasting roles of TNFα in different neurological diseases." (PMID 34511110, 2021).
neurological diseases (continued). "Based on the pivotal role of neuroinflammation in neurological disorders, anti-inflammatory and immunomodulatory agents, as well as anti-TNF agents, have been considered and have shown potential to prevent or alleviate symptoms of psychiatric or neurodegenerative disorders." (PMID 33854417, 2021). "The over-generated oxidants and inflammatory cytokines including reactive oxygen species (ROS), interleukin (IL)-1β, IL-6 and tumor necrosis factor (TNF)-alpha cause neuronal cells apoptosis, impair brain functions, and deteriorate PD and/or other neurological diseases." (PMID 31124458, 2019). "However, in many neurological diseases, microglia can have sustained secretion of inflammatory cytokines and cytotoxic molecules—such as IL-1, TNF-alpha, and nitric oxide—compounded with excessive neuronophagia, can have deleterious effects." (PMID 29548333, 2018). "Regarding regulation of the BBB, the IP-10/TNF-α cytokine axis could be considered a potential target for the development of novel therapeutics in BBB-related neurological diseases." (PMID 29910805, 2018). "Interestingly, three AD genes (ACE, TNF, and MTHFR) were associated with all four of the other neurological diseases." (PMID 28553317, 2017). "It therefore remains to be shown whether targeting TNFα-signaling could have beneficial or detrimental effects for the course of a neurological disease." (PMID 24385951, 2013). "This resulted in an inhibition of neuroinflammation and reduced AD progression in 3xTg-AD mice, and thereby supports the feasibility of targeting TNF-α as a potential treatment strategy for AD and other neurological disorders involving a neuroinflammatory component." (PMID 22642825, 2012). "Therefore, inhibition of TNF-α production is expected to be beneficial in inflammation-related neurological disorders." (PMID 22950459, 2012). "After five years of treatment with TNF-α inhibitor etanercept, the patient was referred for a full neurological assessment after he reported balance disturbances, postural instability, muscle weakness, and other neurological symptoms that indicated the presence of a neurological disorder." (PMID 39459490, 2024). "Upregulated NLRP3 expression may enhance caspase-1-mediated inflammatory cascades and further stimulate the production of downstream inflammatory molecules, including IL-1β, IL-6, and TNF-α, all of which lead to an inflammatory response in a variety of neurological diseases." (PMID 36364939, 2022). "Therefore, understanding the important role of the TNF-α–necroptosis pathway in neuropathic pain may offer novel strategies for the treatment of neurological diseases." (PMID 35806192, 2022). "Since entorhinal denervation was employed in our study to induce homeostatic synaptic strengthening it is conceivable that TNFα-mediated homeostatic synaptic plasticity could be of relevance for a broad range of neurological diseases, which are accompanied by a deafferentation of neurons." (PMID 24385951, 2013). "They attenuate inflammation-induced disorders such as cardiovascular and neurological disorders via down-regulating pro-inflammatory cytokines (IL-6, CRP, COX-2, LPO, TGF-β1, NF-κB, and TNF-α), and pathways (IRAK4, MAPK, JAK/STAT3, TLR4, and ERK)." (PMID 41640995, 2026). "The level of 4 cytokines (TNF-α, IFN-α, IL-6, and monokine induced by IFN-γ) were found to be significantly higher in CHIKV patients with neurological diseases." (PMID 38229040, 2024). "Proinflammatory cytokines, including IFN-γ and TNF-α, and T cells, particularly CD4+ T cells, mediate neurological disease development and mortality in SINV-infected mice." (PMID 37243143, 2023). "However, in some conditions, studies have found that cytokines such as TNFα, IL-1β, and IL-6 can also improve the outcome of diseases such as ADs and that neutralizing or knocking out these cytokines can eventually attenuate the progression of neurological diseases or injuries." (PMID 36353359, 2022).
neurological diseases (continued). "When neuroinflammation cannot be controlled, sustained TNFα can alter BBB permeability and make the neurological diseases or injuries worsen." (PMID 36353359, 2022). "Recent work has shown that blocking pro-inflammatory cytokines, including TNFα, IL-1β, and IL-6, can reduce the permeability of BBB and improve the outcomes of neurological diseases and injuries to a great extent." (PMID 36353359, 2022). "IVIG is suggested to achieve therapeutic effects in GBS via reduction of IL-1, intercellular adhesion molecule-1, and especially TNF-α, which is significantly higher in GBS than other neurological disease controls." (PMID 34539561, 2021). "Specifically, we found 45 predicted miR-34a-5p target genes in the TNF-pathway and 32 in the TGFB-pathway, both of which have been studied in connection to neurological diseases." (PMID 33305319, 2021). "In addition, pre-treating hNSPCs with a gamma-secretase inhibitor, metformin or tumor necrosis factor α (TNFα), co-transplantation of hNSPCs with MSCs or using biomaterial scaffolds as a carrier for hNSPCs have also been reported to improve their therapeutic potential for neurological diseases." (PMID 34827135, 2021). "Of all secreted cytokines, both in experimental and clinical conditions, tumor necrosis factor alpha (TNF-α) together with interleukin 1 beta (IL-1β) and interleukin 6 (IL-6) dominate in the pathogenesis of SCI and other neurological diseases." (PMID 32801994, 2020). "We discovered that 3 out of the 105 AD genes were shared by all five neurological disorders: ACE, MTHR, and TNF." (PMID 28553317, 2017). "Our results, together with other studies, underscore the potential of TNF-α as a potential therapeutic target in TBI and other neurological disorders." (PMID 25879458, 2015). "In the brain, receptors for IL1β, IL6, TNF-α, IFN-γ and MCP1 have been the most widely studied in relation to neuropsychiatric and neurological disorders." (PMID 25592846, 2015). "Thus, administering PEFPs reduced IL-6, TNF-α, and IL-1β in hippocampal cells, inhibited the TNF-α and reduced NF-kB in the brain in different neurological disease models." (PMID 40297338, 2025). "In addition to major cytokines, such as TNFα, IL-1β, IL-6, and their receptors, other cytokines also play an important role in neuroinflammation and neurodegeneration and may provide some promising new targets for clinical application to treat neurological disease and injury." (PMID 36353359, 2022). "Considering that activation of CD40 receptor in microglia leads to expression of iNOS and production of TNF-α and other proinflammatory molecules, benfotiamine's ability to suppress CD40 expression can alleviate inflammation in neurological disorders." (PMID 26388737, 2015). "Contrary to the healthy controls with no neurological disease, one study that evaluated serum inflammatory markers revealed significantly increased TNF-α, IL-6, and leptin levels in patients with PPS." (PMID 25886512, 2015). "Although none of the patients with inactive disease showed neurologic disorder, their counterparts showed higher mean levels of serum TNF-α and IL-1β (41.50 ± 33.98 pg/mL and 20.53 ± 16.00 pg/mL, resp)." (PMID 25548434, 2014). "Given that synaptic function is compromised in a majority of neurological diseases, further understanding of the signaling pathways of netrin, Wnt, TGF-β, and TNF-α may contribute to novel therapeutic approaches for these debilitating disorders." (PMID 24065916, 2013). "In African-Americans, serum TNF-α levels were significantly higher relative to matched controls (P = 0.039), and patients with neurologic disease had significantly higher TNF-α than patients lacking this manifestation (P = 0.022)." (PMID 22195005, 2011). "In support of that, TNF-α and IL-1, inducers of UPP1, alter lipid metabolism and stimulate production of eicosanoids, ceramide and reactive oxygen species that potentiate CNS injuries and certain neurological disorders." (PMID 19763259, 2009).
neurological diseases (continued). "Therefore, targeting miRNAs which negatively regulate TNF signalling or APP expression directly may be used as strategy to prevent accumulation of this protein and subsequent neurological disease." (PMID 34572074, 2021). "In addition, TNFα signaling through the TNFR2 pathway, as is the case in other neurologic disorders, may be involved in dampening excitability, since mice lacking TNFR2 have a higher incidence and greater severity of seizures." (PMID 28497109, 2017). "Although baseline production of IFN-γ was higher in cases with high proviral loads than in control groups, both groups produced high amounts of IFN-γ and TNF, indicating that a high production of proinflammatory cytokines may occur even in the absence of neurological disease." (PMID 32385802, 2020). "Indeed, as outlined in previous sections, especially for neurological diseases more selective approaches are warranted as there is a clear discrepancy between TNFR1 and TNFR2 signaling in the brain typified by the aggravated disease symptoms that are induced by anti-TNF drugs in MS patients." (PMID 29751683, 2018). "Even though the role of TNF-α in neurodegeneration has been widely acknowledged, TNF-neutralizing therapies have failed to treat neurological diseases." (PMID 37391534, 2023). "This theory is supported by significantly elevated levels of serum cytokines IL‐6, TNF‐alpha, and IL‐10 in patients with IAE compared to those with no neurological disorders or not infected with influenza virus." (PMID 33155427, 2021). "Compared to an HIV-1 positive patient without neurological disorder, HAND patients have increased levels of IL-8, the production of which is probably induced by IL-1β and TNF-α through MAPK pathways." (PMID 22727020, 2012).